RUNX2 (RUNX family transcription factor 2)
Diseases named in the same sentence as RUNX2 in open-access papers (continued):
Sharing a sentence is not in itself a finding about the gene and the disease.
breast carcinoma (continued). "Runx2 can maintain the mechanical conditioning of breast cancer cells in softer matrices, a phenomenon that has not been observed with another critical mechanosensitive transcription factor, YAP." (PMID 38791330, 2024). "It was previously confirmed that miR-218 targets 3'UTR of Runx2 and Rictor but the effects of their interaction have not yet been reported in breast cancer." (PMID 37968694, 2023). "For example, human and murine breast cancer-secreted EVs enriched in cadherin 11 (CDH11) and α5 integrin delivered runt-related transcription factor 2 (RUNX2) to the bone, inducing an osteogenic environment and bone lesions that promoted bone colonization by cancer cells." (PMID 37350937, 2023). "In this study, the breast cancer cells expressed high levels of Runx2 and Rictor compared to non-tumorigenic MCF-10A cells which were in line with previous studies." (PMID 37968694, 2023). "RUNX2 expression can also drive tumorsphere formation, a marker of stemness and, in partnership with TAZ, can result in increased shedding of soluble E-cadherin, which in turn can cooperate with HER2 in driving breast cancer cell growth." (PMID 36831308, 2023). "In breast cancer, RUNX2 promotes the nuclear localization of TAZ, but not YAP, and therefore enhances the expression of target genes." (PMID 36429115, 2022). "Furthermore, the upregulation of RUNX2, and the positive correlation between RUNX2 and RBM5-AS1 expression, were validated in breast cancer tissues from StarBase database or collected by us." (PMID 35110544, 2022). "The published breast cancer dataset (GSE48390) revealed a positive correlation between RUNX2, MTA1 and CUL4B, and negative correlations among RUNX2/MTA1/CUL4B and PPARα/SOD2." (PMID 35534547, 2022). "Besides, RUNX2 also can activate Indian Hedgehog expression and further increase PTH1R levels in breast cancer metastatic bone disease." (PMID 35534547, 2022). "RUNX2 can induce EMT and invasiveness of breast cancer cells partly by inhibiting SNAI2 expression." (PMID 35534547, 2022). "Functional experiments demonstrated that RUNX2/NuRD(MTA1)/CRL4B complex could promote EMT and bone metastasis by inhibiting the expression of PPARα and SOD2 in breast cancer." (PMID 35534547, 2022). "Meanwhile, RUNX2 expression was increased by increasing the expression of vascular endothelial growth factor, matrix metalloproteases (MMP2, MMP9, and MMP13), and bone sialoprotein (BSP) in breast cancer metastatic cells." (PMID 36092942, 2022). "Recently, we reported that Runx2 promotes autophagy without significant alterations in the core autophagy-related gene (ATG) expression in bone-derived breast cancer cells." (PMID 35884497, 2022). "In addition, the TF, RUNX2, can promote CD44/CD24 breast cancer stem cell properties and breast cancer tumorigenesis through the EMT process." (PMID 34993131, 2021). "Similarly, we also used the UALCAN database to further analyze the expression levels of RUNX2 and RUNX3 in breast cancer." (PMID 34485309, 2021). "Likewise, the aberrant elevation of Runt-related transcription factor 2 (RUNX2) positively correlated with anti-cancer resistance in various cancers, such as osteosarcomas, breast cancer, and pancreatic cancer." (PMID 34376784, 2021). "RUNX1 and RUNX2 expression in breast cancer was relatively high, ranking second after acute myeloid leukemia (LAML) for all the analyzed tumor types, indicating their potential role in breast cancer." (PMID 34485309, 2021). "Similarly, ectopic expression of Runx2 in MCF10A normal mammary epithelial cells and MCF-7 breast cancer cells can disrupt acini formation and promote epithelial to mesenchymal transition further contributing to tumor progression, respectively." (PMID 34503118, 2021). "Furthermore, we evaluated the expression of tumor-promoting genes that play critical roles in the progression and metastasis of breast cancer, such as MMP9, Runx2, TGFβ, and Snail." (PMID 34230453, 2021).
breast carcinoma (continued). "Interestingly, we also found opposite effects of RUNX2 and RUNX3 gene methylation changes on immune cell infiltration in breast cancer." (PMID 34485309, 2021). "Meanwhile, we also found that the RUNX2 promoter methylation level was significantly lower in breast cancer tissues than normal tissues, regardless of stage, subclass, or histological type." (PMID 34485309, 2021). "Moreover, we found that RUNX2, a stemness marker highly expressed in TNBC and known to play a crucial role in breast cancer metastasis, can be negatively targeted by BETi in TNBC." (PMID 32166583, 2020). "Thus, the miR-205/RUNX2 axis leads to the inhibition of the EMT process, invasion, migration and stemness maintenance in breast cancer." (PMID 33375067, 2020). "In our study, we revealed that through the activation of RUNX2, SET7/9 could promote breast cancer progression in vitro and in vivo." (PMID 32102992, 2020). "Our group also showed that BOLCs (RUNX2- RANKL double positive breast cancer cells) significantly increase in estrogen receptor (ER) positive breast cancers rather than human epidermal growth factor receptor-2 (HER2) positive ones." (PMID 33374380, 2020). "Therefore, we identify that lncRNA-NORAD acts as an oncogenic RNA in the breast cancer tumorigenesis and the lnc-NORAD/TGF-β/RUNX2 axis in the breast cancer tumorigenesis." (PMID 30930692, 2019). "We chose RUNX1 and not RUNX2, since RUNX1 together with its binding partner CBFb has recently been discovered to be mutated ~ 4–6% in breast cancers; suggesting its tumor suppressor function in this context." (PMID 29581836, 2018). "Identification of phosphorylated receptors in human tumors and discovery of phospho-PR-regulated pathways (i.e., including HER2, RUNX2, AR, AHR, and PAX2) suggest novel ways to specifically target breast cancer stem cell (CSC) outgrowth as part of durable breast cancer therapies." (PMID 28412963, 2017). "Moreover, we observed a positive correlation of the mRNA levels between RUNX2 and BRGs (ITGBL1, SPARC and POSTN) in primary breast cancer tissues." (PMID 27806311, 2016). "Endogenous RUNX2 is required to maintain high levels of pAKTS473 in invasive cancer cells, but not in non-invasive breast cancer cells or normal cells." (PMID 26204939, 2015). "Patients with breast cancers expressing high levels of RUNX2 had shorter overall survival (mean survival 130 months in RUNX2-high versus mean survival 152 months in RUNX2-low/negative)." (PMID 24626992, 2014). "Expression levels of RUNX2 and miR-10a/b in108 pairs of tumor and non-tumor tissue of breast cancer were assayed by quantitative PCR analysis and evaluated for their prognostic implications." (PMID 25266482, 2014). "On the other hand, RUNX2 overexpression increased cell migration ability in non-metastatic MCF7 breast cancer cell line." (PMID 25266482, 2014). "Because mmu-mir-30c is known to target Runx2, we addressed whether there is regulatory cross talk between RUNX2, hsa-mir-30c, and NOV in breast cancer cells." (PMID 25120384, 2014). "Although these results are concordant with a small study showing that RUNX2 is absent in ER+ breast cancer, they contrast to one in which RUNX2 expression was specifically found in ER+ tumours." (PMID 24626992, 2014). "Studies of breast cancer revealed regulation of several genes involved in bone invasion, such as MMPs, VEGF, OP, and BSP, by RUNX2, suggesting that this master transcription factor might contribute to bone metastasis in breast tumor." (PMID 25266482, 2014). "Previous studies have shown that Runx factors directly regulate SOST and CSF-2 expression in other cell-types but they are not known targets of Runx2 in breast cancer cells." (PMID 22032690, 2011). "We also examined the expression of two other Runx2-target genes, OPN and Galectin-3, whose expression is strongly associated with metastasis but neither has been shown to be regulated by Runx2 in metastatic breast cancer cells." (PMID 20591170, 2010).
breast carcinoma (continued). "Previous reports have shown that compared to non-metastatic cells Runx2 is overexpressed in the metastatic breast cancer cells, MDA-MB-231." (PMID 20591170, 2010). "Together, our data demonstrate that CBFβ is essential for invasion of metastatic breast cancer cells and that the expression level of Runx2 is not sufficient to overcome the requirement for CBFβ, at least at a subset of Runx2-target genes." (PMID 20591170, 2010). "Interestingly, further studies with an inhibitor of CBFbeta-RUNX interaction resulted in EMT of breast cancer stem cells, suggesting that the loss of RUNX1 rather than increase of RUNX2 causes EMT in early stage breast cancer." (PMID 38630262, 2024). "However, the overexpression of RUNX2 could resist the regulation of mitochondrial damage and ferroptosis-related factors by NGR1 in breast cancer cells, and the effect of NGR1 on breast cancer was enhanced after the down-regulation of RUNX2." (PMID 38885076, 2024). "The study found that Runx2 expression is not restricted to metastatic human breast cancer cell lines (MDA-MB-231) but is also clearly expressed in non-metastatic human breast cancer cells (MCF-7), non-tumorigenic (HC11) cells, and primary mammary epithelial cells." (PMID 37759471, 2023). "This is also supported by data from the METABRIC study, where 14% of primary breast cancer samples were found to harbor alterations in CBFB, while 11%, 5% and 4% of patient samples possessed various categories of genetic alterations in RUNX1, RUNX2 and RUNX3, respectively." (PMID 36831308, 2023). "Therefore, it is suggested that RUNX2/NuRD(MTA1)/CRL4B complex might activate the IL-17 signaling pathway and multiple cytokines to induce bone metastasis in breast cancer." (PMID 35534547, 2022). "In conclusion, we demonstrated that RUNX2 could cooperate with NuRD(MTA1)/CRL4B complex and acted as an inducer in various biological processes, including cell proliferation, invasion, bone metastasis, as well as cancer stemness of breast cancer." (PMID 35534547, 2022). "In virtue of the established ENHs’ plasticity, we may speculate that the remaining 11 elements that were not cooperating for RUNX2 expression in thyroid and breast cancer can be functionally relevant in other settings using different types of interplays." (PMID 34680347, 2021). "The inhibition of miR-1305 expression in TNBC patients may lead to an increase in Runx2 expression via a post-transcriptional mechanism (because we did not identify the correlation between them) that promotes breast cancer aggressiveness." (PMID 31487369, 2020). "Our results demonstrated that the negative correlation between ANCR and RUNX2 expression may be universal in breast cancer patients." (PMID 28978036, 2017). "Based on our finding that RUNX2 expression was modulated by ANCR, we speculated that the expression of ANCR might also be negatively correlated with RUNX2 in breast cancer patients and breast cancer cell lines." (PMID 28978036, 2017). "Given that Runx2 expression is elevated in metastatic bone lesions of breast cancer patients but absent in corresponding primary tumors, employment of a Runx2-activatable therapy should result in maximal iNOS transgene expression in the most aggressive tumor sites and spare normal tissue." (PMID 28325291, 2017). "Similarly, in human breast cancer, RUNX2 directly regulates the expression of MMP9 and MMP13, bone sialoprotein and OPN, IL-8 and the TGFβ-induced PTHrP levels and mediates invasion of the human breast cancer cell lines MDA-MB-231 and MCF7." (PMID 26204939, 2015). "Interestingly, aberrant RUNX2 expression induces EMT-like changes in normal mammary epithelial cells and disrupts normal acini structure in three-dimensional cultures, suggesting a role for RUNX2 in promoting the early events of breast cancer progression." (PMID 26204939, 2015). "However, the effect of crosstalk of Runx2 and PI3K/Akt signaling for survival of breast cancer cells is still unknown." (PMID 24479521, 2014).
breast carcinoma (continued). "However, studies of this transcription factor have been limited to a small number of cell lines, and the role of RUNX2 as a putative oncogene in primary breast cancer has not been demonstrated in vivo." (PMID 24626992, 2014). "We first demonstrated that expression of SOST and CSF-2 could be induced in non-metastatic MCF-7 breast cancer cells by heterologous expression of Runx2." (PMID 22032690, 2011). "Since Runx2 is overexpressed in metastatic breast cancer cells, and there are no reports of CBFβ expression in breast cells, we sought to determine whether Runx2 function in these cells was dependent on CBFβ." (PMID 20591170, 2010). "However, it is not known if the increased expression of Runx2 observed in metastatic breast cancer cells is sufficient to regulate gene expression independently of CBFβ." (PMID 20591170, 2010). "Thus, RUNX2 functions as a master mediator during the transformation of epithelial breast cancer cells into osteomimetic cells under the induction of CAF/BMP2, and the expression of BRGs is repressed by the TGF-β/SMAD/RUNX2 signaling pathway but induced by the BMP/SMAD/RUNX2 signaling pathway." (PMID 27806311, 2016). "We demonstrated that expression of RUNX2 significantly correlated with miR-10a/b in ER negative and triple negative breast cancers and the expression levels of RUNX2 and miR-10a/b individually or jointly were significant prognostic factors for predicting breast cancer recurrence." (PMID 25266482, 2014). "These “educated” osteoblasts express RUNX2/osteocalcin (OCN)/OPN, are negative for IL-6 and α-smooth muscle actin (αSMA), and have new properties where they acquire the capacity to suppress both triple-negative and ER+ breast cancer cell proliferation." (PMID 37296983, 2023). "Interestingly, RUNX2 and AKT were shown to be reciprocally regulated in prostate cancer but not in breast cancer." (PMID 34064589, 2021). "We next investigated whether elevated expression of wild type RUNX2 in MCF7 cells, which are breast cancer cells with limited migratory potential and do not express detectable RUNX2 protein, would alter cell migratory potential." (PMID 21029421, 2010).
osteoporosis (202 papers, 2007 to 2026). A condition of reduced bone mass, with decreased cortical thickness and a decrease in the number and size of the trabeculae of cancellous bone (but normal chemical composition), resulting in increased fracture incidence. "Most importantly, NIBAN2 correlation to RUNX2 alternative splicing and bone loss was verified in osteoporosis patients." (PMID 40051391, 2025). "Our findings offer a novel perspective on the genetic mechanisms underlying osteoporosis by assessing the phase separation status of RUNX2." (PMID 39704037, 2025). "In summary, Niban2 overexpression regulates Runx2 AS and rescues bone loss in OBs during osteoporosis in vivo." (PMID 40051391, 2025). "In osteoporosis, meta-analysis research proved that RUNX2 T > C polymorphisms can affect bone homeostasis in women after menopause and can effectively predict the disease." (PMID 41511334, 2025). "Most importantly, NIBAN2 expression level negatively correlates with RUNX2 spliced isoforms and bone loss in osteoporosis patients." (PMID 40051391, 2025). "It has been found that the expression level of Runx2 gene is associated with skeletal diseases such as osteoporosis and fracture healing." (PMID 39561180, 2024). "The differential DNA methylation of the promoters and regulatory regions of the RUNX2 gene is poorly understood in the context of associative search with osteoporosis itself, as well as with individual endophenotypes: fractures and low BMD levels." (PMID 39000419, 2024). "Identification of CNVs in genes previously associated with osteoporosis (e.g. RUNX2, COL1A2, and PLS3) has confirmed their importance in bone remodelling." (PMID 36795294, 2023). "Application of fusion protein to in vivo mouse osteoporosis model also showed that HAB‐30Kc19α‐RUNX2 enhances bone regeneration, compensating for the bone loss induced by osteoporosis." (PMID 37574255, 2023). "Morroniside increases the expression of Runx2, promotes osteoblast differentiation, and inhibits the osteoporosis caused by ovariectomies." (PMID 37895909, 2023). "Further studies are needed to elucidate the precise molecular mechanisms underlying the link between ANAPC1, RUNX2, and osteoporosis." (PMID 37629076, 2023). "Patients with a heterozygous pathogenic frameshift variant, c.1205dupC, reflecting the role of RUNX2 protein in the maintenance of adult bone, presented with osteoporosis leading to recurrent bone fractures and scoliosis." (PMID 34946295, 2021). "Pretreatment with KDM5A inhibitor JIB-04 partially rescues bone loss during osteoporosis by increasing the H3K4me3 level on the Runx2 promoter." (PMID 32963550, 2020). "It has been found that abnormal expression of many genes can cause osteoporosis, among which RUNX2 is the key transcription factor regulating osteoblast differentiation and bone formation during bone development." (PMID 32293484, 2020). "Variants in LRP5 and RUNX2 variants are also associated with bone mineral density and increased risk of osteoporosis, and osteoporotic fractures in association studies in Caucasians and Asian populations." (PMID 26719974, 2015). "Aberrant DNA methylation, a significant epigenetic change, influences osteoporosis by regulating the expression of genes associated with bone metabolism (e.g., RUNX2, NFATc1, SOST) and modifying immune cell activities, thereby facilitating inflammatory bone loss." (PMID 41282636, 2025). "It is known that the inhibition of ovulation may lead to an increase in the methylation status of the RUNX2 promoter in bone, suppress its transcription, reduce translation, and consequently increase the risk of developing osteoporosis." (PMID 39000419, 2024). "Furthermore, they found that the rs6086746 variant was significantly associated with osteoporosis, by participating on the binding of RUNX2, a master transcription factor involved in the osteoblast maturation." (PMID 38715801, 2024).